KLRG1 (killer cell lectin like receptor G1)
Diseases named in the same sentence as KLRG1 in open-access papers (continued):
Sharing a sentence is not in itself a finding about the gene and the disease.
infection (continued). "Moreover, it was shown that the antigen-specific IL-2+CD4+ T cell subsets were negative for KLRG1, which is a surface marker of terminally differentiated T cells, during Mtb challenge infection." (PMID 30123219, 2018). "However, enhanced numbers as well as enhanced frequencies of KLRG1+ CD8+ T cells were still observed on day 35 post infection although these differences were not significant." (PMID 27875529, 2016). "In order to identify the phenotype of CD8+ T cells generated during this infection/cure under CQ cover regimen, splenocytes and peripheral blood from mice three weeks post last inoculation for the presence of CD8+, CD3+, CD11a, CD127, CD27, KLRG1, CD44 and CD62L cells by flow cytometry was analysed." (PMID 24620841, 2014). "Similarly, the vast majority of effector CD4+ T-bet+ cells from WT mice failed to express KLRG-1 on days 11 or 14 infection." (PMID 23593003, 2013). "TEM, in contrast, reside predominantly in the periphery, usually at the site of primary infection, and possess a terminally differentiated phenotype, characterized by low expression of IL7Rα and CD62L and high expression of killer cell lectin-like receptor G1 (KLRG1)." (PMID 22046127, 2011). "We hypothesized that since KLRG1 expression and the production of IFN-γ by F3 late stage effector CD8+ T cells is IL-12 dependent, CXCR3 expression may also be IL-12 dependent, possibly explaining the attenuation of effector cells to the site of infection in our model." (PMID 26244629, 2015). "Interestingly, we found that OX40 expression on CD8 T cells is largely restricted to the KLRG1-low compartment during LCMV cl13 infection, suggesting that OX40 preferentially acts to maintain higher numbers of these longer-lived effector T cells during the persistent phase of infection." (PMID 22969431, 2012). "Infection-induced TIGIT+ repair Treg cells also did not express the tissue Treg cell markers ST2, KLRG1 or GATA3 at the transcriptional or protein level." (PMID 41094201, 2025). "Forty days after infection, the great majority of CD127+aaMAIT cells also were YFP+, while ~95% of Klrg1+aaMAIT cells were reporter negative." (PMID 37231163, 2023). "On different days post infection (dpi), donor cells in the lungs and spleens were analyzed for CD103, KLRG1, and CD62L expression." (PMID 35942952, 2022). "The OTI-S4KO cells mostly lacked KLRG1 and CD62L expression after infection with both pathogens, indicating a defect during formation of TEFF and TCM cells." (PMID 35942952, 2022). "At 10 dpi, the splenic OT-I were a heterogenous population based on KLRG1 and CX3CR1 but by 6 weeks post infection, when these cells did not express Nur77-GFP there was a more homogeneous (>98%) population of OT-I that maintained a KLRG1+CX3CR1+ phenotype." (PMID 35727849, 2022). "The absolute numbers of KLRG1+ cNK cells in PEC increased in response to cps1-1, but not to RH and ME49 infection." (PMID 27721814, 2016). "Unlike cps1-1 infection, after RH and ME49 infection, KLRG1 on cNK cells was more widely expressed across all maturation subsets." (PMID 27721814, 2016). "Nevertheless, at least 30% of the influenza M1 tetramer positive cells in the older group remained KLRG1 CD57 double negative, and should maintain the ability to respond to infection." (PMID 21887299, 2011). "Blocking at the time of infection and the following day (days 0 and 1, d0–1) led to the highest increase in the frequency and the number of TCF-1+SLAMF6+ stem-like T cells, which were formed in the near absence of KLRG1+ TEFF cell differentiation." (PMID 40062995, 2025). "However, in LM-GP33 infection at day 7, CD43 and CD27 expression did not explicitly mirror the phenotype observed by CD127 and KLRG1 expression." (PMID 38127070, 2023).
infection (continued). "In contrast, the small population of CD8αloCD11ahi CD8+ T cells from mock-infected mice retain a memory-like phenotype (likely virtual memory), expressing little KLRG1 and high levels of CD127 and CD62L, demonstrating that these cells are not activated during mock-infection." (PMID 28231312, 2017). "In the chronic phase, Plasmodium‐specific CD4+ T cells in IL‐27‐neutralized mice consisted mainly of CD127+KLRG1− and CD127−KLRG1+ subpopulations that displayed distinct cytokine production, proliferative capacity, and are maintained in a manner independent of active infection." (PMID 37855243, 2023).
cancer (44 papers, 2013 to 2025). A tumor composed of atypical neoplastic, often pleomorphic cells that invade other tissues. "Studies targeting KLRG1 showed that not only does it serve as a marker of T-cell senescence, but it is also predictive of disease severity and cancer." (PMID 40303366, 2025). "Several studies have shown synergistic effect by blocking KLRG1 and PD-1 together in mouse models for multiple cancer types." (PMID 38241355, 2024). "Tem cells are usually characterized by a CD45RO+C-C motif chemokine receptor 7 (CCR7)-killer cell lectin-like receptor G1 (KLRG1)high phenotype in patients with cancer." (PMID 38576625, 2024). "TSCM cells generally lack KLRG-1 expression, and KLRG-1+ TSCM cells have been associated with cancer patients undergoing relapse." (PMID 39190688, 2024). "The foundation of this observation lies in the EOMES transcriptional signature that we first defined and associated with TIGIT+ KLRG1+ CD8 T cells in T1D responders to teplizumab (anti-CD3) therapy and here extended to HC, cancer, and chronic viral infection." (PMID 38650930, 2024). "The direct recognition, rapid activation, and cytotoxicity of KLRG1 on cancer cells make it an attractive tool for cancer immunotherapy, and this has recently been extensively reviewed." (PMID 38898461, 2024). "In the context of human physiology, KLRG1 has been subjected to thorough investigation across a spectrum of disease states, spanning expedited immune responses to malignant tumor progression." (PMID 38898461, 2024). "Terminal TEX signatures from the mouse and cancer data sets were also more similar to TIGIT+KLRG1+ cells (K-S test, P = 4.3e-03 and P = 9e-06, respectively)." (PMID 38650930, 2024). "Anti-KLRG1 monoclonal antibodies (mAbs) significantly increase the antitumor activity of immune cells and reduce the worsening of disease in cancer mouse models." (PMID 38898461, 2024). "KLRG1 is an immune checkpoint receptor and a combination blockade of KLRG1, and PD-1 promotes immune control of local and disseminated cancers." (PMID 37152010, 2023). "If KLRG1 expression on Tregs is validated in human cancers, it is reasonable to presume that KLRG1+ Tregs will be armed with a similar highly suppressive functional profile as in murine studies." (PMID 35572605, 2022). "Overall, additional studies exploring human Treg KLRG1 expression, especially in cancer settings, will need further examination." (PMID 35572605, 2022). "For example, soluble E-cadherin is reported to activate KLRG1, an inhibitory receptor on immune effector cells, to attenuate the cytotoxic effect to cancer cells." (PMID 33641663, 2021). "The current in vivo KLRG1 neutralization studies confirm that KLRG1 restrains the immune system from cancer defense." (PMID 30858925, 2019). "Here, we report on translational studies of human KLRG1 expression and the in vivo activity of an anti-mouse KLRG1 neutralizing antibody in murine cancer models." (PMID 30858925, 2019). "Because cancer checkpoint immunotherapies induce T cell proliferation, they are predicted to expand the population of KLRG1+ cells, resulting in a homeostatic checkpoint brake on efficacy contributing to adaptive resistance." (PMID 30858925, 2019). "Collectively, we find these findings in accordance with previous data highlighting that a predominant KLRG1+ effector-memory T cell response can be a vital correlate of immunity for the efficacy of therapeutic cancer vaccines or other immunotherapies." (PMID 28388572, 2017). "Moreover, S100A4, S1PR5 and KLRG1, are biomarkers of therapeutic efficacy in mouse cancer models and patients with cancer." (PMID 40574416, 2025). "Akin to chronic viral infection and cancer systems, pop3 (KLRG1-CD62Lhi) exhibits the characteristics of stem-like progenitor CD8 T cells (high Tcf7, Slamf6, and Cxcr5 expression), whereas pop4 (KLRG1+CD62Lhi) closely resembles a transitory subset (elevated Tbx21, low Tcf1, and Tox expression)." (PMID 39975082, 2025).
cancer (continued). "Both 2B4 and KLRG1 have previously been linked to CD8 T cell exhaustion in chronic viral infection and targeting KLRG1 in combination with PD-1 blockade has been evaluated in an in vivo cancer model." (PMID 36818683, 2023). "Given the insufficient knowledge on KLRG1 expression in human Tregs, further studies will be necessary to validate the presence and role of these cells in various human pathological conditions including cancer." (PMID 35572605, 2022). "KLRG1+ Tregs have also been reported to amass in oncogene HPV16 E7-induced hyperproliferative premalignant skin lesions, indicating that KLRG1+ Tregs may regulate HPV-induced epithelial carcinoma." (PMID 35572605, 2022). "In this study, through the analyze of the data from the Gene Expression Omnibus, the Cancer Genome Atlas and the Genotype-Tissue Expression, we found that the expression of KLRG1, BTK, CCR2 and SCML4 was significantly downregulated in LUAD tissues compared to normal controls." (PMID 34187403, 2021). "Overall, the identification of how to modulate the expansion of this population and/or other potent non-KLRG1 CD8+ T cell subsets may prove beneficial for the development of future effective cancer immunotherapies." (PMID 28388572, 2017). "Indeed, KLRG1+CD8+ T cells are excellent predictors of the effectivity of cancer vaccines." (PMID 36796366, 2023). "Furthermore, the novel link between MDSCs and up-regulated expression of CD38 and KLRG1 on T cells and NK cells identified in this study suggests a wider scope of applications for CD38- and KLRG1-blocking drugs in immunotherapies of cancers and inflammatory diseases." (PMID 37207205, 2023). "This view was further cemented by 2011 and 2015 with nomenclature for cancer CD8 T cells characterizing CTLA-4, PD-1, LAG-3, and TIM-3 as marking “exhausted” cells, whereas KLRG1 marked senescent cells." (PMID 39832302, 2025). "Three genes are involved in immune system response to cancer, which clearly indicates that they bear a protective role: PDCD1, KLRG1, and MUC16." (PMID 31568528, 2019). "Although KLRG1 has infrequently been studied among TILS, single cell RNA-seq data indicates abundant KLRG1-expressing TILS across a range of cancer types, and significant numbers (13–26%) of CD8 T cells that do not express PD-1 but do express KLRG1." (PMID 30858925, 2019). "Thus, repressing KLRG1 on human memory T cells might be a novel therapeutics against cancer." (PMID 27557510, 2016). "When examining the surface receptor expression on cancer-patient and healthy individuals’ osteoclasts, decreased expression of MHC-class I, CD54, KLRG1, KIR2, and MICA/B could be seen on cancer patients’ OCs as compared to healthy OCs." (PMID 31878338, 2019). "No anti-mouse KLRG1 antibody with characterized neutralizing function has been available as a reagent for murine model studies, and no murine cancer studies targeting KLRG1 neutralization have been published." (PMID 30858925, 2019). "To comprehensively investigate the immunoinhibitory pathways in T cells, we used FACS to analyze the surface expression of eight IRs (PD-1, Tim-3, BTLA, KLRG-1, TIGIT, 2B4, CD160, and CTLA-4) on T cells from peripheral blood and tumors isolated from 131 cancer patients." (PMID 31709176, 2019). "Very little human cancer data examining KLRG1 expression has been published, and no murine cancer models involving neutralization of KLRG1 have been reported." (PMID 30858925, 2019). "Furthermore, it has been highlighted that a predominant population KLRG1+CD8+ T cells are an optimal effector subset for protective immunity, and likely a vital subset that correlates with the efficacy of cancer immunotherapies." (PMID 28388572, 2017). "Therefore, several selected markers such as CX3CR1, A100A4, KLRG1, S1PR5, and S100A8 were investigated in cancer mouse models and patients with lung cancer to verify the feasibility of utilizing these markers to identify non‐responders and predict immunotherapy efficacy." (PMID 40574416, 2025).
cancer (continued). "Beyond KLRG-1 or Tim-3, it has not been reported whether senescent T cells from cancer patients co-express other iRs." (PMID 34386013, 2021). "Targeting of KLRG1 neutralization in murine cancer models has not previously been reported." (PMID 30858925, 2019). "Importantly, inhibiting KLRG1/AMPK signaling can prevent AMPK activation and reinstate NK cell cytotoxicity, cytokine secretion, proliferation, and telomerase expression, thereby bolstering immunity in aging individuals and in individuals with malignant tumors." (PMID 38898461, 2024). "Moreover, although KLRG-1 expression on NK cells does not necessarily imply senescence, KLRG-1+ NK cells have been associated with reduced effector functions through the activation of the AMP-protein kinase pathway, potentially rendering the host more susceptible to infections and cancer." (PMID 40303366, 2025). "These cells are thought to develop from killer cell lectin-like receptor G1 negative (KLRG1-) memory precursor cells and are crucial for peripheral immunity against re-infection and cancer." (PMID 34611479, 2021).
bacterial infection (4 papers, 2020 to 2023). "In several studies KLRG1 upregulation has been observed on short-lived effector CD8+ T cells during viral and bacterial infection models, suggesting a role for KLRG1 in this context." (PMID 35572605, 2022). "Memory like NK expressing CD27 and KLRG1 developed in a bacterial infection model." (PMID 33370392, 2020). "Regardless, the similarity between Klrg1+aaMAIT cells in mice and human PMBC-derived MAIT cells raises the question as to whether natural bacterial infections in humans influence the state of human MAIT cells." (PMID 37231163, 2023).
infectious disease (4 papers, 2015 to 2024). A disorder directly resulting from the presence and activity of a microbial, viral, or parasitic agent in humans. "Inhibition of KLRG1 expression may become a new method for treating infectious diseases." (PMID 38898461, 2024).
inflammation (3 papers, 2017 to 2025). Aberrant reaction of the microcirculation characterized by movement of fluid and leukocytes from the blood into extravascular tissues. "Upon lung inflammation, both MCMV-specific KLRG1+ and CD127+ OT-I T cells extravasated from the vasculature." (PMID 33479479, 2021). "In contrast, CD25low ILC2s, exhibiting lower surface expression of T1/ST2, ICOS, and KLRG1 and a more modest cytokine production capacity, dominated in our chronic HDM airway inflammation model." (PMID 29250067, 2017).
immune dysfunction (2 papers, 2015 to 2025). "Moreover, the abnormal expression of KLRG1 may regulate other immune cells through its inhibitory signals, further contributing to immune dysfunction." (PMID 40444276, 2025).
GI tumour (1 paper, 2018). "Similarly, ILC1 (p value: 0.01) and ILC2 (p value: 0.0009) populations in malignant GI tumour tissue express significantly elevated KLRG1 compared to paramalignant tissue." (PMID 29587679, 2018).
KLRG1 also shares sentences with these, for which no sentence is quoted: hepatocellular carcinoma (3 papers); breast tumors (2); gastric cancer (2); hematologic malignancies (2); metastatic disease (2); adenoma (1); astrocytoma (1); autoimmune lymphoproliferative syndrome (1); benign tumours (1); cervical intraepithelial neoplasia (1); colorectal (1); colorectal adenocarcinoma (1); dengue (1); esophageal cancer (1); HCMV infection (1); Hypertension (1); IgA nephropathy (1); immunodeficiency (1); inflammatory myopathy (1); muscular dystrophy (1); pemphigus (1); pneumonia (1); primary biliary cholangitis (1); renal cell carcinoma (1); sarcopenia (1); systemic lupus erythematosus (1); urothelial carcinoma (1).